RPS13 (ribosomal protein S13)
Description:
Component of the small ribosomal subunit. The ribosome is a large ribonucleoprotein complex responsible for the synthesis of proteins in the cell. Part of the small subunit (SSU) processome, first precursor of the small eukaryotic ribosomal subunit. During the assembly of the SSU processome in the nucleolus, many ribosome biogenesis factors, an RNA chaperone and ribosomal proteins associate with the nascent pre-rRNA and work in concert to generate RNA folding, modifications, rearrangements and cleavage as well as targeted degradation of pre-ribosomal RNA by the RNA exosome.
Synonyms: S13; uS15
Tractability: Small molecule: an approved drug acts on it; a structure with a bound ligand is known; a high-quality ligand is known. PROTAC: UniProt records ubiquitination sites on it; ubiquitination databases record sites on it; its protein half-life has been measured; a small molecule that binds it is known. Other modalities: a drug acting on it is in phase 2 or 3 trials.
Target class: Other cytosolic protein
Gene: Protein-coding gene on chromosome 11 (17,074,385 to 17,077,727, reverse strand). Ensembl gene ENSG00000110700.
Subcellular location: Cytoplasm; Nucleus, nucleolus
Subcellular location (Human Protein Atlas): Endoplasmic reticulum
Pathways (Reactome):
Metabolism of proteins: Eukaryotic Translation Termination; Formation of a pool of free 40S subunits; Formation of the ternary complex, and subsequently, the 43S complex; GTP hydrolysis and joining of the 60S ribosomal subunit; L13a-mediated translational silencing of Ceruloplasmin expression; PELO:HBS1L and ABCE1 dissociate a ribosome on a non-stop mRNA; Peptide chain elongation; Ribosomal scanning and start codon recognition; SRP-dependent cotranslational protein targeting to membrane; Translation initiation complex formation; ZNF598 and the Ribosome-associated Quality Trigger (RQT) complex dissociate a ribosome stalled on a no-go mRNA
Disease: SARS-CoV-1 modulates host translation machinery; SARS-CoV-2 modulates host translation machinery; Viral mRNA Translation
Metabolism of RNA: Major pathway of rRNA processing in the nucleolus and cytosol; Nonsense Mediated Decay (NMD) enhanced by the Exon Junction Complex (EJC); Nonsense Mediated Decay (NMD) independent of the Exon Junction Complex (EJC)
Cellular responses to stimuli: Response of EIF2AK4 (GCN2) to amino acid deficiency
Developmental Biology: Regulation of expression of SLITs and ROBOs
Metabolism: Selenocysteine synthesis
Gene Ontology:
Molecular function: mRNA 5'-UTR binding; mRNA binding; protein binding; RNA binding; structural constituent of ribosome
Biological process: negative regulation of RNA splicing; ribosomal small subunit biogenesis; cytoplasmic translation; maturation of SSU-rRNA from tricistronic rRNA transcript (SSU-rRNA, 5.8S rRNA, LSU-rRNA); translation
Cellular component: cytoplasm; cytosolic ribosome; cytosolic small ribosomal subunit; extracellular exosome; focal adhesion; membrane; nucleolus; nucleus; postsynaptic density; small-subunit processome; cytosol; nucleoplasm; ribosome
Genetic constraint (gnomAD): Loss-of-function variants: 0 observed, 12.6 expected, observed/expected ratio (o/e) 0, 90% interval 0 to 0.24. The upper end of that interval is the gene's LOEUF score, 0.24, which puts it in group 1 of 6, group 1 being the genes least tolerant of losing a copy. Missense variants: 59 observed, 95.06 expected, observed/expected ratio (o/e) 0.62, 90% interval 0.5 to 0.77. Synonymous variants: 41 observed, 32.58 expected, observed/expected ratio (o/e) 1.26, 90% interval 0.98 to 1.63.
Homologues: Orthologues: dog RPS13 (100% identical), macaque RPS13 (100% identical), mouse Rps13 (100% identical), zebrafish rps13 (97% identical), tropical clawed frog rps13 (88% identical), Drosophila melanogaster RpS13 (87% identical), guinea pig RPS13 (81% identical), Caenorhabditis elegans rps-13 (76% identical).
Diseases named in the same sentence as RPS13 in open-access papers:
RPS13 is named in the same sentence as 26 diseases in open-access papers, as found by Europe PMC text mining. Sharing a sentence is not in itself a finding about the gene and the disease. The quoted sentences say what the papers report.
gastric cancer (12 papers, 2011 to 2025). A primary or metastatic malignant neoplasm involving the stomach. "In gastric cancer, for example, RPS13 has been reported to promote tumour cell growth and both RPS13 and RPL23 have been implicated in chemoresistance, although their value as independent prognostic markers for patient outcome remains to be clarified." (PMID 41589302, 2025). "Further, RPS13 promotes the growth and cell cycle progression of gastric cancer cells by inhibiting p27 expression." (PMID 37062845, 2023). "For instance, ribosomal protein S13 (RPS13) promotes cell cycle progression and cell growth by inhibiting p27 in gastric cancer." (PMID 35711835, 2022). "Down-expression of RPL6 and RPS13 inhibit cell proliferation and cell cycle progression in gastric cancer cells." (PMID 30857280, 2019). "Increased expression level of RPS13 in gastric cancer cells protects the cells from drug induced apoptosis and enhances cell proliferation rates." (PMID 29568375, 2018). "In gastric cancer cell lines, uS15 (rpS13), uL14 (rpL23) and eL6 (rpL6) are able to suppress drug-induced apoptosis and promote drug resistance, whereas eS1 (rpS3a) synergizes with drugs to induce apoptosis." (PMID 28085118, 2017). "Many RPs are found affected in gastric cancer (GC) including RPS13, RPL23, RPS27, RPL6, RPL13 and RPL15." (PMID 34873618, 2021). "Moreover, when ribosomal protein RPS13 which enhanced gastric cancer cell line SGC7901 growth was knocked down by RPS13-specific siRNA, it significantly inhibited SGC7901 cell growth and colony forming ability in vitro and suppressed tumor formation ability in nude mouse." (PMID 22043320, 2011). "Some RPs promote the process of oncogenesis, such as silencing of RPS13 restrains the growth of gastric cancer and down-regulation of RPL6 inhibits the proliferation of gastric cancer." (PMID 26735579, 2016). "For example, RPS3 is involved in the onset of cancer, RPS13 and RPL23 promote the multidrug resistance of gastric cancer cells, and RPL19 is involved in the prognosis of prostate cancer and CRC." (PMID 22272377, 2012).
ovarian carcinoma (2 papers, 2013 to 2025). A malignant neoplasm originating from the surface ovarian epithelium. "In normal ovarian and ovarian cancer cell lines, the respective genes were PPIA, RPS13 (ribosomal protein S13), and SDHA (succinate dehydrogenase complex, subunit A)." (PMID 40943534, 2025). "In the subset of ovarian cancer cell lines, the reference genes were PPIA, RPS13 and SDHA, clearly demonstrating the necessity to select genes depending on the research focus." (PMID 23554992, 2013). "Moreover, in the subset of normal and ovarian cancer cell lines, the respective genes were PPIA, RPS13 and SDHA." (PMID 23554992, 2013).
asthma (1 paper, 2023). "Affinity capture studies indicate interactions between the protein products of RPS13, CCT7, and EPS15 and proteins involved in cell–cell and cell-ECM adhesion molecules relevant for asthma, such as VCAM-1, α4β1 integrin, and fibronectin." (PMID 36835202, 2023).
autoimmune disease (1 paper, 2013). A disorder resulting from loss of function or tissue destruction of an organ or multiple organs, arising from humoral or cellular immune responses of the individual to their own tissue constituents. "The presence of antibodies against RPS13 and PSMA1 in different autoimmune diseases suggests that those autoantibodies are not specifically associated with MG, but could represent a phenomenon associated with autoimmunity in general." (PMID 23483977, 2013).
colon cancer (1 paper, 2013). "In the subset of colon cancer cell lines HSPCB, YWHAZ, and RPS13 were the 3 most stably expressed reference genes." (PMID 23554992, 2013).
colorectal cancer (1 paper, 2024). A primary or metastatic malignant neoplasm that affects the colon or rectum. "In the context of gastric cancer, RPL15, RPL6 and RPS13 exhibited upregulated expressions, while in colorectal cancer, RPS18, RPS23, RPL28 and RPL32 were found to be downregulated, implicating these ribosomal proteins as potential diagnostic markers for gastric and colorectal cancers, respectively." (PMID 39684863, 2024).
cyst (1 paper, 2020). A sac-like closed membranous structure that may be empty or contain fluid or amorphous material. "In Particular, Eya + cyst cells decreased in tj > RpS13 RNAi testes when compared with controls, and this was mainly because of the increase of early stage germ cells." (PMID 32896929, 2020). "To elucidate the roles of RpS13 in Drosophila testes, we knocked down RpS13 in early germ cells with a nos‐Gal4 driver and in cyst cells with a tj‐Gal4 driver." (PMID 32896929, 2020). "We showed that PH3‐positive (PH3+) cells resided far from the hub cells when knocking down RpS13 in cyst cells with the tj‐Gal4 driver." (PMID 32896929, 2020). "We also found that Zfh1 + and Eya+/Zfh1 + cyst cells accumulated in tj > RpS13 RNAi testes." (PMID 32896929, 2020). "Importantly, knockdown of RpS13 in early germ cells and cyst cells led to the accumulation of Rho1." (PMID 32896929, 2020).
fetal growth restriction (1 paper, 2025). A fetus that does not grow beyond the 10th percentile of conventionally accepted weight for gestational age. "For fetal growth restriction (FGR), ribosomal dysfunction, as evidenced by RPS13 downregulation, mirrors mechanisms observed in FGR, where impaired placental nutrient transport drives fetal hypoperfusion." (PMID 40727584, 2025).
Hyperglycemia (1 paper, 2025). An increased concentration of glucose in the blood. "The identified signature genes (RPS13, MRPS5, MRPL21, MRPL22, NDUFS3) not only unravel the molecular cascade linking maternal hyperglycemia to fetal vascular dysfunction but also offer tangible targets for diagnostic and therapeutic innovation." (PMID 40727584, 2025).
hypertensive nephropathy (1 paper, 2021). Kidney damage that results from chronically elevated blood pressure; complications include glomerular damage resulting in proteinuria and hematuria. "Expression variability of 4 candidate genes (YWHAZ, SLC4A1AP, RPS13 and ACTB) was further examined by qPCR in biopsies from patients with hypertensive nephropathy (n = 11) and healthy controls (n = 5)." (PMID 34882702, 2021).
injury (1 paper, 2024). Damage inflicted on the body as the direct or indirect result of an external force, with or without disruption of structural continuity. "Significantly, Rpl7a was identified as a hub gene in a murine model of traumatic brain injury, and increased Rps13 gene levels in microglia and epithelial cells were found to be aging-related in a single-cell sequence study on murine brains." (PMID 38590360, 2024).
ischemic stroke (1 paper, 2019). A stroke disorder caused by obstruction of blood flow to the brain, due to thrombotic (local blood clot formation) or embolic (due to a blood clot or other material traveling from another site) event. "First of all, four proteins were involved in ribosome function during ischemic stroke, namely, RPL26, RPL17, RPL39, and RPS13." (PMID 31223330, 2019).
systemic lupus erythematosus (1 paper, 2013). An autoimmune multi-organ disease typically associated with vasculopathy and autoantibody production. "RPS13 is a cytoplasmic protein and part of the 40S ribosomal subunit, autoantibodies against which have previously been identified by a phage-display technique in patients with systemic lupus erythematosus (SLE)." (PMID 23483977, 2013).
cancer (8 papers, 2012 to 2025). A tumor composed of atypical neoplastic, often pleomorphic cells that invade other tissues. "RPS13 promotes the growth and cell cycle progression of cancer cells by inhibiting the expression of tumor suppressor p27." (PMID 35563580, 2022). "Of the eight housekeeping genes studied, peptidylpropyl isomerase A (PPIA also called cyclophilin A) and ribosomal protein S13 (RPS13), especially in combination, were best suitable to normalize gene expression in cancer and normal tissue." (PMID 25750709, 2015). "In our selection of 25 cancer cell lines, we identified HSPCB, RRN18S, and RPS13 as the most stable expressed reference genes." (PMID 23554992, 2013).
tumor (8 papers, 2011 to 2026). "The total RNA was isolated from additional tumor samples and intact skin, DNase digested, and subjected to MMP1 RT-qPCR, with RPS13 serving as the reference housekeeping gene." (PMID 38891088, 2024). "The most recent report on RG selection in ccRCC shows that PPIA and RPS13 (or their combination) is based on paired tumor control kidney specimens (no metastasized tissue) from 16 (14/2 M/F) ccRCC patients." (PMID 25225161, 2014). "Notably, RPS13 gene expression was not affected in our experiment; this gene was previously reported to have stable expression in various normal and tumor tissues." (PMID 38474347, 2024).
infection (3 papers, 2010 to 2018). The state of being infected such as from the introduction of a foreign agent such as serum, vaccine, antigenic substance or organism. "Interestingly, between days 4 and 6 post-infection, a big difference could be observed in the survival rates between the groups treated with the recombinant virus expressing the target gene sequences (RPS13, Vha26, and alpha COP) compared to the control groups (FHV eGFP, FHV WT, Medium and Water)." (PMID 30018564, 2018).
RPS13 also shares sentences with these, for which no sentence is quoted: prostate carcinoma (2 papers); Autoimmunity (1); developmental delay (1); diabetes (1); leukemia (1); myasthenia gravis (1); schizophrenia (1); stomach cancers (1); Stroke (1); tauopathies (1).